PNPLA3 (patatin like domain 3, 1-acylglycerol-3-phosphate O-acyltransferase )
Diseases named in the same sentence as PNPLA3 in open-access papers (continued):
Sharing a sentence is not in itself a finding about the gene and the disease.
liver fibrosis (continued). "Furthermore, the higher presence of the Patatin like phospholipase domain-containing protein 3 (PNPLA3) polymorphism in this population contributes to more advanced degrees of hepatic fibrosis." (PMID 37892625, 2023). "Notably, genetic polymorphism of TM6SF2 in the dominant model was independently linked to the risk of developing NAFLD, and PNPLA3 genetic variants additively increased vulnerability to NAFLD‐related hepatic fibrosis." (PMID 36403577, 2023). "Thus, another explanation was that PNPLA3, which has been linked to multiple lipid metabolic processes and liver fibrosis, bridged the association between BA metabolism and MASLD development." (PMID 37759756, 2023). "Thus, I148M variation in the PNPLA3 gene by regulating hepatic stellate cells is a risk factor for the development of severe hepatic fibrosis." (PMID 37753315, 2023). "Notably, these associations remained significant even after adjustment for common renal risk factors, presence of liver fibrosis and the PNPLA3 rs738409 genotype." (PMID 35733806, 2022). "However, the overactivation of these healing processes leads to the onset of progressive liver fibrosis, especially in individuals with increased susceptibility to liver fibrosis due to gene polymorphisms, such as PNPLA3, TM6SF2, and HSD17B13." (PMID 35563210, 2022). "For instance, the SERPINA1 gene with genotypes MZ and MS, in this case, represents a protective factor for the development of fibrosis, whereas, for example, the polymorphism of the PNPLA3 rs738409 C > G gene is a risk factor for both liver fibrosis and the development of HCC." (PMID 36013566, 2022). "In addition to the genetic mutations that predispose individuals to hepatic fibrosis that appear in childhood, mutations of the PNPLA3 gene have been described as a major predisposing factor in non-alcoholic fatty liver disease (NAFLD)." (PMID 34025430, 2021). "However, even in Brazil, the PNPLA3 polymorphisms have also been implicated in liver fibrosis in patients with NAFLD and chronic hepatitis C." (PMID 33622266, 2021). "Males and participants with the GG variant of the PNPLA3 gene had higher values of liver fibrosis." (PMID 34065978, 2021). "The I148M variant of PNPLA3 is a single nucleotide polymorphism, which is related to a variety of liver and cardiovascular diseases and their complications (such as non-alcoholic fatty liver disease, liver fibrosis, coronary artery disease)." (PMID 34476007, 2021). "This work aimed to assess transforming growth factor-β1 (TGF-β1), and patatin-like phospholipase domain containing-protein 3 (PNPLA3) genetic variants as risk factors for hepatic fibrosis and hepatocellular carcinoma (HCC) in Egyptian patients with HCV-related liver cirrhosis." (PMID 34711009, 2021). "As our previous research has determined differential associations between carbohydrate intake and liver fat by PNPLA3 genotype, we were particularly interested in how the PNPLA3 genotype impacts the association between diet and liver fibrosis in this current cohort." (PMID 34065978, 2021). "In addition, NASH patients with PNPLA3 GG alleles had a higher level of aspartate aminotransferase (AST) and advanced liver fibrosis compared to patients with PNPLA3 CC alleles." (PMID 34299189, 2021). "Interestingly, liver stiffness and the prevalence of liver fibrosis were also significantly higher in participants with the GG PNPLA3 allele." (PMID 34065978, 2021). "A single nucleotide polymorphism PNPLA3 rs738409 c.444C>G was identified as a risk factor for concurrent liver steatosis and a faster liver fibrosis progression in patients with chronic HCV infection in the past, but its impact on the need and timing of LT has not been evaluated." (PMID 31527889, 2019).
liver fibrosis (continued). "Collectively, our findings uncover I148M PNPLA3 as an additional interesting contributor of impaired cholesterol and lipid metabolism in human HSCs, predisposing to exacerbated proinflammatory phenotype and enhanced hepatic fibrosis severity in humans." (PMID 31497741, 2019). "In our previous study we demonstrated by transient elastography that the PNPLA3 polymorphism might be associated with increased liver stiffness, a surrogate marker of liver fibrosis, in patients with chronic liver diseases." (PMID 30161167, 2018). "Since PNPLA3 SNP rs738409 has been reported to be associated with liver fibrosis and PNPLA3 SNPs rs738409 and rs2281135 have been associated with elevated transaminases in CCHC participants, correlation analysis between these two SNPs and APRI scores was performed." (PMID 26950933, 2016). "However, the possible effect would be much less strong than that exerted by other genetic variants, such as those influencing insulin receptor signaling and the PNPLA3 rs738409 SNP, which were significantly associated with liver fibrosis in the same series." (PMID 20825652, 2010). "Furthermore, carriers of the PNPLA3 G allele show increased fibrosis due to the loss of retinyl-palmitate lipase activity in hepatic astrocytes and inhibition of retinol production, which suppresses liver fibrosis." (PMID 40074353, 2025). "A clinical implication from this finding is that genetic susceptibility may override modifiable environmental factors in patients diagnosed with NAFLD and patients with risk alleles in PNPLA3 may benefit from additional intensive surveillance to prevent hepatic fibrosis progression." (PMID 36403577, 2023). "Finally, we found that the major risk PNPLA3 allele G for NAFLD was also associated with higher liver fibrosis stage and lower eGFR, thereby confirming observations from previous studies, showing the potential impact of this genetic polymorphism on the link between NAFLD and CKD." (PMID 35733806, 2022). "Therefore, PNPLA3 gene is a strong predisposing genetic factor for hepatic fibrosis." (PMID 34025430, 2021). "Additionally, we ran combined analysis to assess whether TM6SF2 and MBOAT7 SNPs mediate the risk of liver fibrosis or liver cirrhosis in the presence of certain PNPLA3 genotypes." (PMID 30875804, 2019). "Thus, it is plausible to speculate that the association of the I148M Pnpla3 gene in HSCs with liver fibrosis is mediated via the production of GM-CSF, which promotes neutrophil survival and activation." (PMID 29552626, 2018). "Our study demonstrates that the impact of genetic risk variants in PNPLA3 and TM6SF2 on liver fibrosis is essentially dependent on the presence of metabolic dysfunction or significant alcohol consumption." (PMID 41492318, 2026). "Upon univariable analyses, risk variants in PNPLA3 and TM6SF2 were associated with liver fibrosis as assessed by LSM (log-transformed), with a stronger association in the Tertiary-care cohort than the At-risk cohort." (PMID 41492318, 2026). "Researchers have also discovered that treating mice with antisense oligonucleotides targeting the PNPLA3 gene suppressed the expression of the PNPLA3 I148M variant, slowed the progression of NAFLD, and improved liver fibrosis." (PMID 40881642, 2025). "In this study, we evaluated the association between the PNPLA3 variant rs738409 and MBOAT7 variant rs641738 and the risk of hepatic fibrosis or liver cirrhosis in MASLD etiology." (PMID 40650184, 2025). "In multivariate analysis, the independent factors associated with significant liver fibrosis were VCTE, M2BPGi, and PNPLA3 rs738409." (PMID 40002828, 2025). "The advent of refined techniques in isolating HSCs has made PNPLA3's direct role in HSCs for liver fibrosis development more apparent." (PMID 39394864, 2025).
liver fibrosis (continued). "In a well-characterized Southern European cohort of 146 MASLD patients, liver fibrosis was assessed using the FIB-4 index, serum BAG3 levels were quantified by ELISA, and genotyping for PNPLA3 and TM6SF2 variants was performed." (PMID 41373448, 2025). "Then, we assessed the association with H. pylori and G-allele PNPLA3 with non-invasive markers of liver fibrosis, focusing on the MASLD G-allele PNPLA3-positive cohort (n: 92/116, 79%)." (PMID 39312529, 2024). "Although the mechanism by which PNPLA3 rs2896019 promotes liver fibrosis remains to be elucidated, a mechanism similar to that of rs738409 is possible." (PMID 39713746, 2024). "The proportions of participants with different severities of liver fibrosis in different genotypes of PNPLA3 rs738409 C>G were assessed (p = 0.003, FDR corrected p-value = 0.012)." (PMID 38674389, 2024). "Logistic regression analysis for the association of PNPLA3 rs738409 C>G with MASLD and liver fibrosis in MASLD showed statistical significance with an increased odds ratio." (PMID 38674389, 2024). "In this study, we investigated the effect of PNPLA3-I148M on the activation of hepatic stellate cell line LX-2 and the progression of liver fibrosis." (PMID 37298640, 2023). "T2D (OR = 4.67; 95%CI 2.13–10.20; p < 0.001), PNPLA3 rs738409 and TM6SF2 rs58542926 polymorphisms (OR = 3.94; 95%CI 1.63–9.54; p = 0.002) were independently related with advanced liver fibrosis." (PMID 35625751, 2022). "In summary, we found that the presence of T2D or significant IR, defined by a new proposed cut-off of HOMA-IR > 5.20, on top of PNPLA3 rs738409 and TM6SF2 rs58542926 polymorphisms were associated to advanced liver fibrosis." (PMID 35625751, 2022). "We found that being a carrier of the G variant of PNPLA3 increased 5-fold the probability of NASH and 4-fold the probability of liver fibrosis." (PMID 36110512, 2022). "Subsequently, we examined any potential role of PNPLA3 rs738409 and TM6SF2 rs58542926 variants in moderating predisposition to significant and advanced hepatic fibrosis, and liver cirrhosis in separate analyses." (PMID 36028802, 2022). "Liver fibrosis was positively associated with plasma HA and PIIINP, as well as with the presence of the risk allele G of PNPLA3 rs738409 variant, and negatively with eGFR." (PMID 35733806, 2022). "Several studies have found that mutation in the genes associated with hepatic lipid metabolism, including PNPLA3, predispose to the development of NAFLD, hepatic fibrosis, and HCC in the presence of a metabolic disorder condition." (PMID 36266438, 2022). "Our study explains, to some extent, the interindividual differences, showing that the degree of liver fibrosis differed significantly depending on PNPLA3 genotype, both before treatment and after three monthspost-SVR." (PMID 34833371, 2021). "Collectively, our data clearly report that hepatic PNPLA3 expression is significantly induced during liver fibrosis development and it is more abundant in carriers of G/G genotype." (PMID 32043752, 2020). "It has also been further demonstrated that in HSCs, retinol release is dysregulated by PNPLA3 148M, which further enables excessive hepatic fibrosis in the context of NASH." (PMID 33036387, 2020). "Based on our previous observation that PNPLA3 expression was induced during primary human HSCs activation in vitro, we evaluated PNPLA3 expression during liver fibrosis development in human NASH biopsies." (PMID 32043752, 2020). "All together, we stress that our preliminary data on in vivo PNPLA3 expression during liver fibrosis progression require future validations also in non‐metabolic hepatic disorders." (PMID 32043752, 2020). "Host genetic predispositions, such as genetic variants of interleukin 28B (IL-28B), patatin-like phospholipase domain-containing 3 (PNPLA3) and other immunogenetic profiles, have also been recognized as potential determinants of liver fibrosis progression." (PMID 30305682, 2018).
liver fibrosis (continued). "Recently, an association between the PNPLA3 I148M polymorphism and histologic liver damage (NASH and liver fibrosis) has been reported." (PMID 22140488, 2011). "We evaluated whether HLA-DRB1, PNPLA3, SLCO1B1, and MTHFR variants are associated with NAFLD, liver fibrosis, or MTX toxicity/pharmacokinetics in RA, after accounting for clinical covariates." (PMID 41753255, 2026). "In this study, we explore the significance of BAG3 detection in patients’ sera in hepatic fibrosis within the context of MASLD and its interaction with key genetic variants PNPLA3 and TM6SF2, aiming to unravel potential new insights into the molecular mechanisms driving disease progression." (PMID 41373448, 2025). "In addition to individual associations, we explored the potential combined effect of PNPLA3 and MBOAT7 variants on liver fibrosis using a logistic regression model that included both polymorphisms." (PMID 40650184, 2025). "Similarly, when using LSM, the progression of liver fibrosis was reported in 8.1%, 13.2% and 23.2% of patients with PNPLA3 CC, CG and GG genotypes, respectively, with an adjusted odds ratio of 1.90." (PMID 39412170, 2025). "Furthermore, all PNPLA3 rs738409 genotypes showed progression of liver fibrosis over 4 years; however, genotype GG showed a greater degree of liver fibrosis progression and worse insulin resistance than the other genotypes." (PMID 40074353, 2025). "Furthermore, GG genotypes of PNPLA3 rs738409 and rs2896019 were factors for liver fibrosis (FibroScan‐aspartate aminotransferase score > 0.35) independent of cardiometabolic criteria." (PMID 39713746, 2024). "Risk alleles in PNPLA3 additively conferred risk of hepatic fibrosis in participants with NAFLD at baseline, regardless of muscle mass or other metabolic risk factors." (PMID 36403577, 2023). "In those already diagnosed with NAFLD, it may be beneficial to take into account the PNPLA3 genetic variant in individualizing surveillance, as it may be more influential in progression to NAFLD‐related hepatic fibrosis than environmental factors." (PMID 36403577, 2023). "Independent associations between eGFR values (included as a continuous measure) and plasma levels of either PIIINP (model 1) or HA (model 2), adjusted for age, sex, systolic blood pressure, PNPLA3 rs738409 genotype, and stages of liver fibrosis in children with NAFLD." (PMID 35733806, 2022). "Hypermethylation of CpG99 in the regulatory region of the patatin-like phospholipase domain-containing protein 3 (PNPLA3) gene and hypomethylation of CpG26 in the regulatory region of the parvin beta 1 (PARVB1) gene have been associated with advanced hepatic fibrosis in patients with NAFLD." (PMID 35844554, 2022). "We observed that the PNPLA3 I148M variant did not have any significant impact on clinical outcomes, progression of liver fibrosis, dominant stricture development, hepatobiliary cancer risk, the need for liver transplantation or patient survival." (PMID 36454904, 2022). "Considering the risk allele frequency of PNPLA3 p.I148M variant in the present sample set, these analyses had sufficient power (> 95%) to detect genetic influences on hepatic fibrosis but not on liver cirrhosis (power of study < 50%)." (PMID 36028802, 2022). "Moreover, eGFR showed significant inverse associations with HA and PIIINP levels, as well as the presence of G of PNPLA3 rs738409, and liver fibrosis stage." (PMID 35733806, 2022). "We found that the PNPLA3 I148M variant did not significantly impact clinical outcomes, liver fibrosis, DS development, hepatobiliary cancer risk, need for transplantation, or survival." (PMID 36454904, 2022). "Therefore, we aimed to evaluate rs738409 patanin-like phospholipase domain-containing protein (PNPLA3) and rs499765 FGF21 polymorphisms in T2D, and their association with NAFLD, liver fibrosis, and serum biomarkers (FGF21 and cytokeratin 18 levels)." (PMID 35630668, 2022).
liver fibrosis (continued). "Interestingly, in the context of hepatic fibrosis, cells overexpressing PNPLA3 promoted immune cells chemotaxis (monocytes and macrophages) as compared to their wild type PNPLA3 carriers." (PMID 35814741, 2022). "Although a trend was observed between PC1 in plasma PL and liver fibrosis in multivariable logistic regression analyses (adjusted for BMI, age and PNPLA3 (I148M) genotype) (OR: 1.18, 95% CI: 0.95, 1.45, P = 0.13), no further associations were observed (data not shown)." (PMID 35083257, 2021). "The TM6SF2 rs58542926 E167K variant is also associated with hepatic fibrosis and cirrhosis, independent of potential cofounding factors such as body mass index (BMI), type 2 diabetes mellitus, and the PNPLA3 rs738409 genotype." (PMID 34503201, 2021). "Of the 10 participants with liver fibrosis, 8 were male and 2 were female (chi-square p = 0.03); additionally, 1 participant had the CC genotype, 2 had the CG genotype, and 7 had the GG genotype in the PNPLA3 gene (chi-square p = 0.06)." (PMID 34065978, 2021). "Liver fat, sex, and PNPLA3 genotype were all shown to be biological predictors of liver fibrosis." (PMID 34065978, 2021). "Moreover, the presence of the genetic variant I148M contributes to characterize the stage and severity of hepatic fibrosis, thus supporting PNPLA3 genotype evaluation as a gold standard for better and specific prognosis." (PMID 32043752, 2020). "Since PNPLA3 GG homozygotes are a risk factor, even when examined in patients only with liver cirrhosis, PNPLA3 SNP GG homozygotes present a high risk of hepatocarcinogenesis independent of liver fibrosis." (PMID 32785100, 2020). "Collectively, our findings expand the suitable range of targets for down-regulating the pro-fibrotic actions of I148M PNPLA3 in HSCs and therefore may contribute to inhibit the onset and progression of liver fibrosis." (PMID 33218077, 2020). "Future studies are required to decipher whether AQPs are targetable within HSCs activation, in order to develop new treatments for liver fibrosis in PNPLA3 I148M patients." (PMID 29116096, 2017). "Even though PNPLA3 rs738409 has been widely studied in different chronic liver diseases, the influence of this polymorphism on liver fibrosis progression in HIV/HCV-coinfected patients has not been consistently established." (PMID 27973562, 2016). "Recently, a cell specific PNPLA3 function linking PNPLA3 to liver fibrosis has been shown." (PMID 27596100, 2016). "Advanced liver fibrosis was neither associated with PNPLA3 (p = 0.253) nor IL28B-genotype (p = 0.628), but with HCV-GT3 (p = 0.003), higher BMI (p = 0.008) and higher age (p = 0.007)." (PMID 26599080, 2015). "This may indicate another possible functional involvement of PNPLA3 in the progression of liver fibrosis by influencing the circulating hyaluronic acid levels." (PMID 22719876, 2012). "This is the first study to investigate the relationship between the PNPLA3 rs738409, TM6SF2 rs58542926, GCKR rs1260326 and rs780094, MBOAT7 rs641738, HSD17B13 rs72613567, and MTARC1 rs2642438 polymorphisms in the Brazilian population with MASLD and liver fibrosis." (PMID 40650184, 2025). "The association of PNPLA3 I148M with MAFLD was independently confirmed a few years later and in numerous studies which have gone on to link the variant to important liver disease phenotypes, including elevated serum transaminases, liver fibrosis, and hepatocellular carcinoma." (PMID 38247511, 2024). "The rs3747207 is situated on the patatin-like phospholipase domain containing 3 (PNPLA3) gene, representing an intron variant that has been associated with various phenotypes such as type 2 diabetes, cholesterol measurements, triglyceride, liver fibrosis, AST, hepatic cancer and MASLD." (PMID 39858580, 2024).